HMGB1 (high mobility group box 1)
Diseases named in the same sentence as HMGB1 in open-access papers (continued):
Sharing a sentence is not in itself a finding about the gene and the disease.
tumor (continued). "In some cancers, the increased expression of HMGB1, detected as a transcript or protein, has been associated with tumor progression." (PMID 34966671, 2021). "Functional experiments implicated that low KDM4D ESCC tumors depended on HMGB1 to potentiate the tumor stemness." (PMID 34820329, 2021). "Activation of the AIM2 inflammasome during the pathogenesis of PAAD caused HMGB1 release, which conferred an immunosuppressive tumor microenvironment and led to tumor cell immune evasion." (PMID 34150748, 2021). "HMGB1 expression was not only related to disease progression, but also closely related to tumor-associated myeloid cells." (PMID 34257571, 2021). "Studies have declared that HMGB1 expression is associated with tumor lymphangiogenesis and new lymphatic vessel formation." (PMID 34456716, 2021). "HMGB1 that is produced by tumour cells interacts with TLR4 on platelets, causing their activation, adhesion, and release of pro-metastatic factors, resulting in metastasis in mice." (PMID 34771442, 2021). "Enhanced oxidative stress then caused CRT exposure and the release of DAMPs including HMGB1, which would then activate DCs for systemic anti-tumor immune responses." (PMID 33420008, 2021). "We sought to investigate the transcriptomic profile of the tumor to better understand the impact of HMGB1 on tumor development in autophagy-deficient livers." (PMID 32382012, 2020). "What’s more, phosphorylation- RIP3 and MLKL activation induced by P. aeruginosa infection resulted in tumor cell necrotic cell death and HMGB1 production, indicating that P. aeruginosa can cause immunogenic cell death." (PMID 33643911, 2020). "The expression of HMGB1 was also positively and significantly associated with tumor expression of mRNA encoding the pro-invasive, proteolytic enzyme, matrix metalloproteinase 9 (MMP-9), both of which correlated significantly with metastatic potential." (PMID 32664328, 2020). "HMGB1 has been reported to induce tumor-associated macrophage polarizing to M2 macrophages through the NF-κB signaling pathway." (PMID 33015161, 2020). "Metastasis and large tumor size are correlated with high telomerase activity and enhanced HMGB1 and HMGB2 levels, and shown to be associated with lower patient survival." (PMID 33076532, 2020). "The main product of this necrotic cell death is extracellular release of high mobility group box 1 (HMGB1), a hallmark of immunogenic cell death and the anti-tumor immune response, and a vital contributor to dendritic cell activation in this context." (PMID 32455916, 2020). "Prior studies have revealed that HMGB1 is persistently associated with hypoxia to promote tumor metastasis." (PMID 32436353, 2020). "Tim-3 suppresses antitumor response via non-T cell mechanisms involving Tim-3/Tim-3 ligand interactions, such as the interaction between tumor-associated dendritic cell-derived Tim-3 and HMGB1." (PMID 33178839, 2020). "In the present study, we confirmed that hypoxic primary tumors cause tumor cells to secrete HMGB1 and further promote neutrophil polarization to the CD62Ldim phenotype via the TLR2 signaling pathway, thereby promoting the formation of tumor metastases." (PMID 32943604, 2020). "HMGB-1 has been associated with cancer hallmarks, including tumor proliferation, invasion, and angiogenesis." (PMID 33167343, 2020). "Since alterations in the expression of HMGB1 and its sub-cellular translocation are associated with the regulation of tumor development and cancer treatment, we propose that HMGB1-mediated autophagy activation is a possible target for chemotherapy." (PMID 33158052, 2020). "Our data, therefore, identify a key role of HMGB1 in promoting autophagy-deficient tumor growth via novel mechanisms." (PMID 32382012, 2020). "Macrophages can be recruited into HCC tissue to become tumor-associated macrophages (TAMs) by upregulation of HMGB1 and then take part in the cancer progression and metastasis." (PMID 32626741, 2020).
tumor (continued). "The role of HMGB1 SNPs in cancer risk, disease progression, and tumor development remains controversial." (PMID 33023053, 2020). "Here, we demonstrated that high mobility group box 1 (HMGB1) is upregulated in patients with cancer, and implicated in a tumor-supportive role." (PMID 32328193, 2020). "The presence of heightened levels of HMGB1 in human tumor tissues and in the circulation is frequently associated with disease severity and progression." (PMID 33013860, 2020). "Specifically, HMGB1/RAGE signalling has been implicated in sustaining an inflammatory tumour microenvironment that supports hepatic oval cell and carcinoma proliferation as well as tumour invasion and metastasis." (PMID 32697038, 2020). "Positive cytoplasmic HMGB1 expression was associated with a poor tumor grade in the CRC cohort (P < 0.05)." (PMID 33122771, 2020). "Abundant evidence, both clinical and experimental in origin, has implicated HMGB1/RAGE interactions in potentiating tumor invasion." (PMID 32664328, 2020). "As a substantial contributor to ICD, HMGB1 activates the immune system by being released from dying tumor cells and prompts the cross-presentation of tumor-associating antigens through its ligation and triggering of TLR4 on dendritic cells (DC)." (PMID 32698492, 2020). "Although CXCL12 and HMGB1 are overexpressed by different tumors and are associated with tumor progression and metastasis, the functions of the CXCL12/HMGB1 heterocomplex in cancer remain to be elucidated." (PMID 33072091, 2020). "There are reports that radiotherapy can also produce antitumor benefits in a manner associated with the release of HMGB1, thereby licensing or restoring tumor immunosurveillance capabilities of CD8+ T cells against tumor cells." (PMID 30744691, 2019). "Blood loss, transfusion, tumor stage, nodal status, and HMGB1 expression were identified as predictors with univariate analysis." (PMID 31399104, 2019). "HMGB1 expression was positively associated with tumor size, parametrial infiltration, the depth of cervical stromal invasion and FIGO stage (P=0.003, 0.019, 0.013, and 0.003, respectively)." (PMID 30962261, 2019). "HMGB1 can mediate the tumor development via RAGE receptor downstream of its release because codeletion of RAGE delayed the tumor development in autophagy-deficient livers." (PMID 31731454, 2019). "In the relationship of HMGB1 to tumor stromal cells, cancer-associated fibroblasts (CAF) were reported to induce HMGB1 expression in cancer cells and promote doxorubicin resistance." (PMID 31905926, 2019). "This suggests that treatment-mediated killing on tumor cells causes HMGB1 passive release from dead cells." (PMID 30988279, 2019). "In the TME, the interaction between TIM-3 and high-mobility group box 1 (HMGB1) prevented activation of tumor associated DCs by impeding sense of immunogenic nucleic acids, thereby suppressing anti-tumor responses." (PMID 31156651, 2019). "We found that HMGB1 expression was associated with tumor recurrence after postoperative radiotherapy in locally advanced ESCC patients." (PMID 30755598, 2019). "HMGB1 expression was significantly associated with tumor size, parametrial infiltration, the depth of cervical stromal invasion, and FIGO stage (P=0.003, 0.019, 0.013, and 0.003, respectively)." (PMID 30962261, 2019). "CXCL11 and HMGB1 protein levels were assessed in 100 tumor tissues by IHC, and analyzed for associations with clinical outcomes." (PMID 30744691, 2019). "In a pancreatic ductal adenocarcinoma (PDAC) cohort, high serum HMGB1 levels proved to have diagnostic potential, besides positively correlating with stage of disease, presence of metastasis, tumor size and worse prognosis." (PMID 31379812, 2019). "In this work, we showed that high HMGB1 expression in tumor tissue is associated with recurrence after PORT for locally advanced resected ESCC." (PMID 30755598, 2019).
tumor (continued). "Based on our results, the tissue HMGB1 mRNA level can be suggested as a novel diagnostic marker with a high sensitivity for HNSCC tumor tissue." (PMID 30245980, 2018). "We recently demonstrated that increased serum concentrations of C-reactive protein (CRP), heat shock proteins (HSPs), and high-mobility group box-1 (HMGB1) were associated with advanced tumor stage and worse outcome." (PMID 29774108, 2018). "TLR4 is highly expressed on innate immune cells, thus the primary responders to RT-associated HMGB1 are likely macrophages and DCs in the tumor microenvironment." (PMID 30692991, 2018). "First, necrosis releases danger-associated molecular patterns (DAMPs), particularly HMGB-1, into the extracellular space, thereby inducing inflammation and promoting tumor progression." (PMID 29636841, 2018). "The peculiar characteristic of ICD is the ability to favor recognition and elimination of dying tumor cells by phagocytes in association with the release of pro-inflammatory molecules (such as cytokines and high-mobility group box-1)." (PMID 29462947, 2018). "Virus-based therapies can have multiple therapeutic effects including tumor cell death, increased anti-tumor immune response, and release of damage- associated molecules like high mobility group box 1 (HMGB1)." (PMID 30366424, 2018). "Here, we showed that ERK-mediated Drp1 phosphorylation is necessary for resisting chemotherapeutic cytotoxicity and reported for the first time that this mediation was associated with extracellular HMGB1 released from dying tumor cells." (PMID 30258050, 2018). "Several studies suggest a role of HMGB1 in enhancing expression and activation of topoisomerase II alpha in pRb-deficient tumor cells." (PMID 29472602, 2018). "Necrotic tumor cells can release intracellular antigens and damage-associated molecular patterns (DAMPs) such as heat shock proteins (HSPs) and high mobility group box 1 (HMGB1) from cytosol and nucleus, which can stimulate systemic immune responses." (PMID 30583459, 2018). "Our findings suggested the tissue HMGB1 protein and mRNA levels as a novel diagnostic marker with a high sensitivity to define the biologic margin of the tumor." (PMID 30245980, 2018). "Pearson's χ2 or Fisher's exact tests demonstrated that HMGB1 expression was associated with tumour stage (p=0.050), histological type (p<0.001) and the addition of adjuvant chemotherapy (p=0.002)." (PMID 29254158, 2017). "Conditional genetic ablation of either single or both alleles of HMGB1 in the pancreas renders mice extremely sensitive to oncogenic K-Ras-driven initiation of precursor lesions at birth, as well as tumor metastasis/invasion at six weeks." (PMID 28374746, 2017). "In immunocompetent mouse models of colon cancer, release of HMGB1 upon 5-FU chemotherapy or surgery has been associated with recruitment of MDSC to the tumor site, promoting inflammation, tumor growth and vascularization." (PMID 29064420, 2017). "The dead malignant cells will release tumour-associated antigens and damage-associated molecular patterns (DAMPs) such as high mobility group box 1, nucleotides, or heat shock proteins that can produce an immunogenic response." (PMID 29348907, 2017). "Tumor necrosis gives rise to an increase in expression of inflammatory mediators including high mobility group box 1 (HMGB1), damage-associated molecular patterns (DAMPs), uric acid, and ATP/UTP." (PMID 28629173, 2017). "Then, we investigated the mechanism underlying the promotion of tumor growth in the Renca-bearing mice model by HMGB1." (PMID 28968989, 2017). "High-mobility group protein B1 (HMGB1) has been implicated in numerous tumour types where expression regulates tumour cell growth and survival." (PMID 29254158, 2017). "HMGB1 has been shown to activate pro-inflammatory signals in the literature and promote autophagy of tumor-associated myeloid cells such as MDSCs57." (PMID 29062041, 2017).
tumor (continued). "Western blot analysis confirmed loss of HMGB1 protein expression in metastatic or invading tumor from liver, lung, and kidney." (PMID 28374746, 2017). "Through the binding with its receptors, such as RAGE or TLRs, HMGB1 has been associated with tumor-cell survival, progression, and metastasis." (PMID 27836008, 2016). "As the most abundant and well-studied HMG protein, HMGB1 is indicated to be associated with ten functional capabilities that drive tumor development and growth." (PMID 27391431, 2016). "The migration of endothelial cells is necessary for angiogenesis and tumour growth and HMGB1 overexpression is associated with an increased angiogenic potential of the endothelial cells." (PMID 26682011, 2016). "It has become evident that EP has pharmacological anti-inflammatory effect to inhibit multiple early inflammatory cytokines and the late inflammatory cytokine HMGB1 release, and the anti-tumor activity is likely associated with its anti-inflammatory effect." (PMID 27980458, 2016). "We assessed the association of HMGB1 SNP genotypes with GC clinical outcome using the multivariate Cox regression analysis with adjustment for age, sex, tumor site, Lauren classification, differentiation, TNM stage and ACT." (PMID 27116470, 2016). "A different study showed that cancer-associated fibroblasts induce HMGB1 (high mobility group box 1), a chromatin-associated nuclear protein released from dying tumor cells that has been suggested to mediate cancer progression and resistance to doxorubicin." (PMID 26828520, 2016). "Mechanistically, hypoxia-induced HMGB1 release seems to be associated with several tumour-promoting events." (PMID 27426915, 2016). "The Kaplan-Meier analysis (log-rank test) showed that HMGB1 overexpression in both the peritumoral liver tissues and the tumor tissues was associated with worse OS (p < 0.001 and p = 0.028, respectively)." (PMID 27836008, 2016). "HMGB1 is implicated in maintenance of genomic stability, autophagy, immune regulation, and tumor growth." (PMID 26925422, 2016). "Although in our study tumor cells appeared to be the major source of HMGB1, the possibility that stromal cells as cancer-associated fibroblasts contributed to its production cannot be excluded." (PMID 26925422, 2016). "The increasing evidences suggest that elevated HMGB1 is associated with tumor metastasis and poor prognosis, making HMGB1 an attractive tumor biomarker." (PMID 27116470, 2016). "In a cohort of 232 breast carcinoma patients treated with anthracycline-based adjuvant chemotherapy, loss of nuclear HMGB1 has been positively associated with tumor size." (PMID 26300886, 2015). "Although chemotherapy-induced HMGB1/TLR4 signaling has primarily been associated with anti-tumor immune responses, HMGB1 has also been shown to promote cancer regrowth and metastasis in cells that survived chemotherapy." (PMID 26486085, 2015). "Necrosis, for example, as induced by a repeated freeze-thaw process, causes tumor cells to release HMGB1 as well as other cellular components such as heat shock proteins (HSP) 70 and 90, mitochondria, cellular membrane, RNA, DNA and uric acid." (PMID 26343191, 2015). "Tumor cells deficient in HMGB1 exhibit compromised capacity to induce ICD and anti-tumor immune responses, however, TLR4 agonists rescued the chemotherapy-induced anti-tumor immune responses." (PMID 26486085, 2015). "HMGB1 is an endogenous signal referred to as a damage-associated molecular pattern (DAMP) molecule that is released from tumor cells and thought to be related to various inflammatory disorders." (PMID 24837834, 2014). "Necrosis of tumor cells can release HMGB1, which can cause chronic inflammation in the tumor microenvironment and help tumor cells survive, grow and metastasize." (PMID 24837834, 2014).
tumor (continued). "Overexpression and cytoplasmic localization of HMGB1 is associated with the proliferation and metastasis of many tumor types, particularly in conjunction with the receptor for advanced glycation end products (RAGEs)." (PMID 23866030, 2013). "The extracellular receptors of HMGB1 include RAGE and TLR4, with RAGE being implicated as a major receptor for HMGB1 in tumor development." (PMID 23766911, 2013). "HMGB1 expression was also closely associated with tumor size, pT stage, nodal status, metastasis status, TNM stage, and poor prognosis." (PMID 23866030, 2013). "As expected, the overall diagnostic value according to tumor stage was correlated to these results; the P values of HMGB1 and CEA according to TNM stage were 0.0018 and less than 0.0001, respectively." (PMID 22496788, 2012). "In present study, we demonstrated that high expression of HMGB1 was associated with incomplete tumor encapsulation and advanced TNM stage." (PMID 22747650, 2012). "Chemotherapeutic agents such as doxorubicin and oxaliplatin can cause massive tumor cell death and tissue damages, releasing various danger signals, such as high-mobility group protein B1 (HMGB1), calreticulin (CRT), and adenosine triphosphate (ATP)." (PMID 22778760, 2012). "Along the same line, cyclophosphamide has been recently reported to cause CRT translocation and HMGB1 release in some types of tumor." (PMID 22400040, 2012). "Co-expression of RAGE and HMGB1 has been found in a majority of metastatic cases, in tumor cells and associated stromal cells." (PMID 19292913, 2009). "HMGB1 is reported to interact with TIM-3 on dendritic cells associated with tumor microenvironments and it is presumed that TIM-3 could negatively regulate innate immune responses promoted by HMGB1 and triggered by nucleic acids." (PMID 41483156, 2026). "Irrespective of a possible type of action, our ranking order of tumors according to their rate of HMGB1 deficiency describes the tumor entities that might benefit most from potential future drugs for targeting HMGB1-deficient tumors." (PMID 40804938, 2025). "Local induction of ICD not only increases tumor cell immunogenicity, but also promotes the release of soluble mediators such as ATP, HMGB1 and other endogenous danger-associated molecular patterns (DAMPs) that trigger pro-inflammatory responses and promote recruitment and activation of immune cells." (PMID 39706891, 2025). "HMGB1 deficiency in <10% was seen in 52 other tumor categories." (PMID 40804938, 2025). "NE can enter tumor cells and degrade tumor suppressors or remodel the extracellular matrix, while HMGB1 (a damage-associated molecular pattern) engages receptors like RAGE/TLR4 on hepatoma cells to activate NF-κB signaling, activating a pro-survival, pro-proliferation program." (PMID 41516032, 2025). "These therapeutic modalities promote immunogenic cell death, enhancing tumor-associated antigen presentation and stimulating the release of damage-associated molecular patterns (DAMPs), including ATP, HMGB1, and calreticulin (CRT), thereby facilitating immune cell recruitment and activation." (PMID 41377584, 2025). "For instance, HMGB1 is strongly associated with cell survival and proliferation and may directly contribute to tumor cell metastasis due to its capacity to enhance cell migration." (PMID 40877572, 2025). "Moreover, although the antitumor efficacy of ADVNE and ADVPPE was diminished in HMGB1-deficient tumor models, they still retained some antitumor activity, likely because of their ability to induce pyroptosis in tumor cells." (PMID 40082916, 2025). "In addition, several biomarkers are associated with tumor-promoting signaling pathways and adverse clinical outcomes; for instance, cathepsin D, miR-421, and HMGB1 are frequently overexpressed in osteosarcoma and linked to enhanced tumor progression." (PMID 40864783, 2025).